IRF3 (interferon regulatory factor 3)
Diseases named in the same sentence as IRF3 in open-access papers (continued):
Sharing a sentence is not in itself a finding about the gene and the disease.
tumor (continued). "In contrast, acute activation of the cGAS-STING pathway often leads to anti-tumor immunity through TBK1-dependent activation of IRF3 and canonical NF-κB p65/p50 signaling, which mediate the transcription of type I IFN signaling." (PMID 38167338, 2024). "Next, we aimed to determine if TRAF6-mediated proliferation of 5-FU-resistant GC cells and tumor growth were affected by IRF3." (PMID 39706834, 2024). "The GAS-STING pathway, upon recognizing cytosolic dsDNA, initiates IRF3 and NF-κB-driven pathways to induce proinflammatory macrophages polarization and strengthen anti-tumor immunity." (PMID 36879291, 2023). "At the endpoint, the levels of cleaved-caspase-3, Ki-67, VSV-G, and IRF3 were further examined in the subcutaneous xenograft tumor sections by immunohistochemistry (IHC) staining." (PMID 37880243, 2023). "Niraparib activated anti-tumor CD8+T cells in the tumor microenvironment through the STING/TBK1/IRF3 pathway in EGFR-mutant NSCLC." (PMID 36865554, 2023). "Following that, STING recruits TBK1 to activate IRF3 inducing the proinflammatory response to enhance innate and adaptive immunity, which is critical in anti-microbial infection and anti-tumour activities." (PMID 37162544, 2023). "On the contrary, we found that treatment with GPC3144‐152 peptide in the co‐culture of CD8+ T cells with TYST or TYST‐sh‐cGAS cells significantly enhanced the levels of TBK1 and IRF3 phosphorylation in these tumor cells, even after silencing cGAS." (PMID 37986544, 2023). "cGAS/STING/IRF3 pathway is known to play a critical role in innate immune response and anti-tumor immunity." (PMID 38057852, 2023). "In summary, upregulated ALKBH5 plays an oncogenic role in HNSCC by inhibiting RIG-I-mediated IFNα secretion via the IKKε/TBK1/IRF3 pathway, which ultimately reduces immune-killing cell infiltration and promotes tumor progression." (PMID 35395767, 2022). "Next, we investigated the effects of the SGLT2 inhibitor on T cell infiltration in vivo and confirmed that the SGLT2 inhibitor activated the STING/IRF3/IFN-β pathway in murine K7M2 tumor cells." (PMID 35662245, 2022). "Recent studies suggest that extracellular HSP90α induces MyD88-IRAK complex-associated IKKα/β-NF-κB/IRF3 and JAK2/TYK2-STAT-3 signaling pathways in macrophages to promote tumor M2 polarization." (PMID 36158677, 2022). "qPCR analysis of the dissociated tumour cells revealed that the delivery of immRNA‐loaded RBCEVs led to the up‐regulation of Ddx58, Mda5, Mavs, Irf3, Irf7, Ifnb, Rsad2, and Isg56 in the tumours." (PMID 35430766, 2022). "Future study should clarify the effect of the IRF3 dimerization on its full transcriptome and how this event is functional for the tumor escape from the immune system attack." (PMID 36572679, 2022). "Researchers found that tumor-derived DNA was the ligand of STING pathway and was associated with phosphorylation of TBK1 and IRF3 and STING-dependent IFN-β." (PMID 35720348, 2022). "IRF3 is a transcription factor that is usually activated in tumor cells through phosphorylation, dimerization, or nuclear translocation." (PMID 33479394, 2021). "They showed that the activation of cGAS, STING, and interferon regulatory factor 3 (IRF3) was tumor-DNA-dependent and contributed positively to dendritic cell activation." (PMID 34072037, 2021). "In another important research, IFN-β1 was specifically upregulated in CAFs that contacted tumor cells through STING/IRF3 pathway activation due to the transcytosis of tumor cell cytoplasm into CAFs." (PMID 35265630, 2021). "These 19 de novo variants were present in non-coding regions including those of tumor associated genes ATR, RPS6KA2, IRF3, and CHD3 22–26." (PMID 34011996, 2021).
tumor (continued). "Activation of the STING pathway can induce an innate immune response and tumor rejection mediated by phosphorylation of IRF3 and inducing strong production of IFN-α/β35." (PMID 34921236, 2021). "IHC analysis showed a positive association between IRF3 and IRF7 expression and tumor-infiltrating immune cells, including CD4+ T cell and CD68+ macrophages." (PMID 34488791, 2021). "Consistent with this, sophoridine has been shown to polarize tumor-associated macrophages (TAMs) into M1-TAMs and suppress M2-TAMs polarization through the TLR4/IRF3 axis." (PMID 34646828, 2021). "In a recent study, subcutaneous injection of STINGVAX to mice bearing B16 tumor cells was associated with STING-dependent IRF3 and type I IFN expression, and tumor regression." (PMID 34070756, 2021). "Meanwhile, Abx treatment inhibited the expression of type I interferon (IFNβ), and ISGs (MX1, ISG15, and IFIT1) in small intestine and tumor tissues, validating its regulation on IRF3 activation." (PMID 33188184, 2020). "Consistently, in vivo MRI analyses revealed that IRF3+/+ → IRF3−/− mice had significantly increased tumor burden than IRF3−/− → IRF3+/+ mice." (PMID 33188184, 2020). "Tumor tissues were then divided into groups with high and low levels of IRF3, TCF1, and LEF1 according to IHC scores." (PMID 33188184, 2020). "We simultaneously analyzed the phosphorylation/activated state of STAT3, Akt, Erk1/2, and p38 in the distal colon and tumor tissues from IRF3+/+, IRF3–/–, IRF3fl/fl, and IRF3fl/flVillincre mice following AOM/DSS treatment." (PMID 33188184, 2020). "We identify IRF3 as a tumor suppressor via inhibiting Wnt signaling, by an unexpected function that departs from its well-known role as transcription factor." (PMID 33188184, 2020). "The results indicates that inhibition of NEAT1 results in the increase in cGAS, STING level, and upregulation of phosphorylation of TBK1 and IRF3 in both of cell lines and tumor samples." (PMID 32296457, 2020). "Tumor harboring IRF3−/− genetic modification grew faster and gained marked weight after transplantation." (PMID 33188184, 2020). "The cGAS-STING pathway can be activated by tumor cell-derived DNA, and STING- or IRF3-deficient mice showed defects in priming CD8+ T cells and tumor control." (PMID 33633744, 2020). "Apcmin/+IRF3−/− mice displayed both more tumors and increased tumor load in the whole small intestine." (PMID 33188184, 2020). "Consistent with our previous observations, tumor tissue analyses also showed increased levels of both phospho-p65 and nuclear IRF3, supporting STING activation in vivo." (PMID 32198351, 2020). "Loss of IRF3 has been linked to age-related cell senescence, and a robust type I IFN response is associated with tumor regression and control." (PMID 32179480, 2020). "Enhanced tumor formation of IRF3-knockout H1299 cells was also abolished by ICG-001 treatment, as well as Wnt signaling activation." (PMID 33188184, 2020). "Substantially, more tumors and markedly increased tumor loads in colons of IRF3−/− mice were observed." (PMID 33188184, 2020). "We found that an anti-TGFβ treatment allowed DMXAA to induce the activation of IRF3, the production of IFNα/β, and to facilitate tumor regression in Spont-PyMT mice." (PMID 31511510, 2019). "As expected, ssRNA and dual-function vector therapy significantly promoted the expression of TLR7 and the phosphorylation of IRF3 and NF-κB in tumor tissues." (PMID 31849942, 2019). "To corroborate the involvement of IFN-I in LCMV-mediated tumour regression, we used Irf3−/−xIrf7−/− mice, which lack IFN-I induction after LCMV infection." (PMID 28248314, 2017). "Studies about IRF-3 revealed it is a tumor suppressor gene in cancer cells, directly or indirectly inhibiting cell growth." (PMID 29100282, 2017). "Recently, studies uncovered IRF-3 emerged as a key tumor suppressor in DNA damage response and cancer cell growth inhibition." (PMID 29100282, 2017).
tumor (continued). "The expression of both STING and IRF3 in the tumor tissues was obviously up-regulated by cGAMP treatment." (PMID 26754564, 2016). "For spleens from tumor bearing old mice majority of the upstream regulators are either interferons (IFNγ, IFNα, IRF3, IRF7, and IFNA2) or are related to the immune system (IKBKB, CHUK, NFκB, NFκBIA, STAT3, and mir-21) and are predicted to be up-regulated." (PMID 26497558, 2015). "Single-cell analyses revealed cell-type-specific functions of IRF3: in tumor cells, IRF3 may suppresses immune-activating gene expression and modulates proliferation; in tumor-infiltrating T/NK cells, IRF3 negatively regulates pro-inflammatory signaling." (PMID 42245669, 2026). "Moreover, in subcutaneous tumor tissues derived from C9orf50‐knockout cells, phosphorylation of IRF3 was also significantly enhanced." (PMID 41472851, 2025). "cGAS-STING-TANK-binding kinase 1-interferon regulatory factor 3 (TBK1-IRF3) signaling pathway leads to immune cell-mediated tumor suppression by recognizing DNA released into the cytoplasm during chromosomal instability thereby regulating gene expression and inducing apoptosis." (PMID 40191727, 2025). "Moreover, similar to NTT tumours, YUMM1.7OVA RTT tumours with Ptgs2 KO or IRF3/7 overexpression were controlled in Rag2–/–Batf3–/– mice, which lack cDC1s." (PMID 39604727, 2025). "A potentially relevant hypothesis in this context is that the relative strength of activation of the IRF3 versus NF-kB downstream signaling arms may impact anti-tumor activity versus tumorigenic and tolerability issues." (PMID 40216780, 2025). "Results proved that STING, phosphorylated STING (pSTING), phosphorylated TANK-binding kinase 1 (pTBK1), and phosphorylated interferon regulatory factor 3 (pIRF3) are up-regulated in tumor tissues after 131I-Mn/SAE@M treatments, confirming the activation of the STING signaling pathway." (PMID 40968370, 2025). "In conclusion, these results suggest that POLE mutations may impede tumor growth and trigger anticancer immune responses through the STING/TBK1/IRF3 signaling pathway." (PMID 38238314, 2024). "In a xenograft tumor model, treatment of IFN‐β or IFN‐γ inhibited tumor growth of wild‐type but not cGAS‐ or IRF3‐deficient B16‐F10 cells." (PMID 39004913, 2024). "IRF3 acts as both a tumor promoter and suppressor in different studies." (PMID 39384770, 2024). "We show that tumor cells have an increased expression of several markers (CD47, IL7R, NKG7, CD80, CD84, CSF1R, NLRC5/CITA, CD2 and IRF3) that may be involved in regulating the level of immune infiltration and the effect on tumor immunity." (PMID 39001353, 2024). "BCG activates two main inflammatory pathways: the TRIF/IRF3/IFNα/β pathway, which has a uniformly pro-immunogenic and anti-tumor role, and the NFκB/TNFα signaling pathway, which mobilizes immunogenic/anti-tumor but also immunosuppressive/tumor-promoting mediators in bladder cancer TME." (PMID 38667314, 2024). "Similarly, the coimmunoprecipitation of both STING and TBK1 with IRF3 was improved in R‐MCF7 cells when tumor cells were treated with MK2206." (PMID 39023171, 2024). "Notably, BIBR1532 intensifies the damage inflicted by IR on DNA, thereby enhancing the phosphorylation of STING, TBK1, and IRF3 proteins in both tumour cells and dendritic cells (DCs)." (PMID 38816831, 2024). "However, the role of IRF3 and NF-κB in the context of tumor cell resistance to chemotherapy remain elusive." (PMID 39706834, 2024). "IRF3 exhibited a moderate level of expression in both tumor and normal samples." (PMID 38240703, 2024). "However, some reports suggest that cancer cells with elevated cGAS/STING/IRF3 protein levels in tumor progression and metastasis exhibit enhanced cGAS-STING pathway activation, which induces mitochondrial outer membrane permeability and triggers apoptosis." (PMID 37354378, 2023).
tumor (continued). "Since IRF3, a tumor suppressor, and E2F1 and NR2C2, cancer promoters, have been reported to be important in cancer, investigation of the action of KIAA1324 in the regulation of these target genes is essential for understanding KIAA1324-related cancer development deeply." (PMID 37612293, 2023). "After viral infection of tumor cells, cell cycle regulatory proteins, oncogenes, tumor suppressor genes, and key signaling components in innate signaling pathways in tumor cells including IRF3 and STAT are activated." (PMID 37040283, 2023). "TAMs-related functions are also regulated by several genes, including C-C motif chemokine ligand 2 (CCL2), C-C motif chemokine ligand 18 (CCL18), TANK-binding kinase 1 (TBK1), and IFN regulatory factor 3 (IRF3), whose signaling pathway is activated during tumor angiogenesis." (PMID 36432658, 2022). "Meanwhile, IRF3 overexpression promoted YAP-dependent tumor development." (PMID 35037825, 2022). "In this study, IRF3 knockout resulted in tumor rejection partially or completely, suggesting that IRF3 may play a critical role in immunosuppression." (PMID 34768716, 2021). "Interestingly, among all IRF factors, the mRNA and protein expression levels of IRF3 and IRF7 were significantly upregulated in tumor tissues and associated with poor OS in CRC patients." (PMID 34488791, 2021). "We evaluated their replication competence in cancer cells as well as their ability to elicit T cell responses against tumor neo-antigens, demonstrating the feasibility to obtain replication-efficient VACVs with an increased capacity to activate the IRF3 pathway." (PMID 34553028, 2021). "Therefore, STING also recognizes tumor-DNA and induces downstream signaling of NF-κB and interferon regulatory factor 3 (IRF-3)." (PMID 34557197, 2021). "Indeed, in the small cell lung cancer mouse model, PARP or CHK1 inhibition significantly potentiated the anti-tumor effect of PD-L1 blockade via STING mediated IRF3 activation, thereby inducing type I IFNs production and innate immune activation." (PMID 33214545, 2020). "We found that the mRNA level of IRF3 increased in CRC tissues and was associated with tumor stages." (PMID 31949493, 2020). "Overexpressed IRF-3 drove NK cells to express type I interferon, chemokine and costimulatory molecules, hence enhancing their tumor-suppressing functions, including cell proliferation, release of perforin and granzyme M, and cytotoxicity toward tumor cells." (PMID 32489584, 2020). "On the other hand, it is also reasonable that the accumulation of YAP/TAZ, usually caused by the dysregulation of Hippo-YAP pathway, might dampen the TBK1, IRF3 activation, and the anti-tumor responses." (PMID 32174922, 2020). "Consistently, ICG-001 treatment downregulated the proliferation of IRF3-knockout cells to a level similar with wild-type cells, and tumor formation assays phenocopied this observation, with marked decrease of Ki67-positive cells and reduced Wnt signaling activation." (PMID 33188184, 2020). "Therefore, our data identify IRF3 as a tumor suppressor and a prognosis marker of the CRC patients with an unexpected mechanism." (PMID 33188184, 2020). "The axis IRF3/IFN-γ has been described as a pivotal immune mechanism in anti-tumor responses." (PMID 33381445, 2020). "Consistently, another study also revealed that the CD8+ T-cell response to tumor-associated antigens was diminished in both STING-deficient and IRF3-deficient mice; these data suggest that host-cell STING and IRF3 are required for spontaneous CD8+ T-cell activity against immunogenic tumors." (PMID 31679519, 2019). "In addition, the Tank-binding kinase 1 (TBK1), which is responsible for the phosphorylation of IRF3, was phosphorylated in both tumor models after DMXAA treatment." (PMID 31511510, 2019).
tumor (continued). "The inconsistency may derive from the diverse post-translational modification of IRF-3, e.g., phosphorylation and sumoylation, and different regulation of IRF-3 by cytokines and chemokines involved in the tumor microenvironment." (PMID 28566697, 2017). "It was recently reported that IRF-3 might function as a tumor suppressor in tumorigenesis by inhibiting growth of cancer cell in vitro and in vivo." (PMID 28566697, 2017). "IRF-3 is essential for the anti-tumor pathogenesis in some cancer cells." (PMID 28566697, 2017). "For example, TFs, such as ASH1L, CFLAR, HMGB3, ZNF160 and MATR3, displayed opposite behaviors on some cytokines; inflammatory factors; nuclear and tumor factors, such as IL-2, IL-6, NF-κB, and Irf3; immunogenic nucleic acids; papillomavirus E7/E6; caspase-3/caspase-8; Toll-like receptor; and so on." (PMID 28719625, 2017). "Strikingly, in both STING-deficient and IRF3-deficient mice, there was a substantially diminished CD8+ T cell response against tumor-associated antigens and, in wild-type mice, transfer of tumor DNA to host APCs resulted in TBK1 and IRF3 phosphorylation and, as a consequence, production of IFN-β." (PMID 29050360, 2017). "To further investigate whether cGAMP targets the STING in the cGAS-cGAMP-STING-IRF3 pathway to facilitate antitumor activity, we examined the expression of STING and IRF3 in tumor tissues treated with cGAMP by immunofluorescence assay." (PMID 26754564, 2016). "Moreover, in accordance with our in vitro results, tumours treated with poly I:C showed nuclear localization of IRF-3, confirming the activation of this transcription factor in LNCaP xenografts." (PMID 25444175, 2015). "IRF3 was expressed in the nucleus in 52.9% (45/85) of HCC tumor sections." (PMID 25884709, 2015). "Previous studies showed the constitutively active forms (serines replaced by phosphomimetic aspartate amino acids) of human IRF-3 protein exerts the ability to modulate the apoptotic and anti-tumor properties after being delivered by recombinant adenovirus into macrophages." (PMID 21936899, 2011). "IRF-1 and IRF-3 have been shown to regulate TRAIL transcription in tumor cell lines." (PMID 19404407, 2009). "In conclusion, the transcription factor IRF3 plays a key role in the generation of stromal cells in the stromal region, but not tumor cells in the tumor region, and the underlying programme involves in inhibition of cell proliferations by arresting cells in the G1/S phase." (PMID 38729966, 2024). "Furthermore, IRF3 acts as a tumor promoter by activating YAP to exacerbate GC progression." (PMID 39384770, 2024). "Knocking out Irf3, Irf7, Gsdme or Ripk3 in B16F10 tumor cells each reduced DAC’s effectiveness at inducing immune control of the tumor, which indicates that the derepression of multiple innate immune pathways helped to restore immune control." (PMID 41315764, 2026). "This corresponded with the strongest activation of the cGAS-STING pathway in tumor lysates, as evidenced by maximal expression of p-TBK1, p-IRF3, and IFN-β." (PMID 41356181, 2026). "Mechanistically, TRIM59 interacts with interferon regulatory factor 3 (IRF3) and promotes its ubiquitination and proteasomal degradation, thereby inhibiting the IRF3-STING pathway and downstream anti-tumor interferon production." (PMID 42245669, 2026). "Activated TBK1 phosphorylates IRF3, promoting its nuclear translocation and initiating IFN-α/β transcription, which rapidly recruits CD8+ T cells and NK cells to elicit anti-tumor effects." (PMID 41019083, 2025). "Intratumoral ADU-S100 induced IRF3 phosphorylation and IFNβ expression within 4 h, indicating the rapid activation of the STING pathway in the tumor microenvironment." (PMID 40897896, 2025). "Conversely, SURF4 overexpression in T cells significantly reduced the expression of activation markers (CD3D, CD69) and anti-tumor proteins (GZMB), while simultaneously suppressing the p-STING/p-IRF3 axis." (PMID 40846839, 2025).